RN7SKP89 (RN7SK pseudogene 89)
Gene: Miscellaneous RNA gene on chromosome 5 (114,253,513 to 114,253,754, forward strand). Ensembl gene ENSG00000222706.
Homologues: Orthologues: chimpanzee 7SK (99% identical). Paralogues in human: RN7SKP79 (81% identical), RN7SKP180 (80% identical), 7SK (79% identical), RN7SKP124 (78% identical), RN7SKP211 (78% identical), RN7SKP243 (78% identical), RN7SKP146 (77% identical), RN7SKP203 (77% identical), RN7SKP28 (77% identical), RN7SKP80 (77% identical), RN7SKP176 (77% identical), RN7SKP25 (77% identical), and 283 more.